H3C10 (H3 clustered histone 10)
Description:
Core component of nucleosome. Nucleosomes wrap and compact DNA into chromatin, limiting DNA accessibility to the cellular machineries which require DNA as a template. Histones thereby play a central role in transcription regulation, DNA repair, DNA replication and chromosomal stability. DNA accessibility is regulated via a complex set of post-translational modifications of histones, also called histone code, and nucleosome remodeling.
Synonyms: H3FK; HIST1H3H; H3/k; H3F1K
Gene: Protein-coding gene on chromosome 6 (27,810,051 to 27,811,300, forward strand). Ensembl gene ENSG00000278828.
Subcellular location: Nucleus; Chromosome
Subcellular location (Human Protein Atlas): Nucleoplasm
Pathways (Reactome):
Gene expression (Transcription): B-WICH complex positively regulates rRNA expression; DNA methylation; ERCC6 (CSB) and EHMT2 (G9a) positively regulate rRNA expression; MLL4 and MLL3 complexes regulate expression of PPARG target genes in adipogenesis and hepatic steatosis; NoRC negatively regulates rRNA expression; PRC2 methylates histones and DNA; RNA Polymerase I Promoter Escape; RNA Polymerase I Promoter Opening; RUNX1 regulates genes involved in megakaryocyte differentiation and platelet function; RUNX1 regulates transcription of genes involved in differentiation of HSCs; Regulation of endogenous retroelements by KRAB-ZFP proteins; Regulation of endogenous retroelements by Piwi-interacting RNAs (piRNAs); Regulation of endogenous retroelements by the Human Silencing Hub (HUSH) complex; SIRT1 negatively regulates rRNA expression; Transcriptional regulation by small RNAs
Chromatin organization: CHD1 and CHD2 subfamily; CHD6, CHD7, CHD8, CHD9 subfamily; ChAHP complex assembly; Chromatin modifying enzymes; HATs acetylate histones; HDACs deacetylate histones; HDMs demethylate histones; Interaction of NuRD complexes with transcription factors; NuRD complex assembly; PKMTs methylate histone lysines; RMTs methylate histone arginines
Disease: Defective pyroptosis; Dengue Virus-Host Interactions; HCMV Early Events; HCMV Late Events
Signal Transduction: Activated PKN1 stimulates transcription of AR (androgen receptor) regulated genes KLK2 and KLK3; Estrogen-dependent gene expression; Formation of the beta-catenin:TCF transactivating complex; Pre-NOTCH Transcription and Translation
Developmental Biology: Activation of anterior HOX genes in hindbrain development during early embryogenesis; Chromatin modifications during the maternal to zygotic transition (MZT); Transcriptional regulation of granulopoiesis
Immune System: FXIIa activates plasma kallikrein-kinin system; Interleukin-7 signaling; Regulation of PD-L1(CD274) transcription
and 8 more pathways
Gene Ontology:
Molecular function: cadherin binding; protein binding; structural constituent of chromatin; nucleosomal DNA binding; DNA binding; protein heterodimerization activity
Biological process: epigenetic regulation of gene expression; nucleosome assembly; chromatin organization; heterochromatin formation; telomere organization
Cellular component: chromatin; extracellular exosome; membrane; nucleoplasm; nucleosome; nucleus; protein-containing complex; extracellular region; chromosome
Genetic constraint (gnomAD): Loss-of-function variants: 9 observed, 7.18 expected, observed/expected ratio (o/e) 1.25, 90% interval 0.74 to 1.87. That is too few expected variants to judge how well the gene tolerates losing a copy. Missense variants: 163 observed, 211.23 expected, observed/expected ratio (o/e) 0.77, 90% interval 0.68 to 0.88. Synonymous variants: 122 observed, 85.43 expected, observed/expected ratio (o/e) 1.43, 90% interval 1.23 to 1.66.
Homologues: Orthologues: Drosophila melanogaster His3:CG33812 (99% identical), zebrafish si:ch1073-153i20.2 (99% identical), zebrafish si:ch211-113a14.20 (99% identical), zebrafish si:ch211-113a14.23 (99% identical), zebrafish si:ch211-113a14.27 (99% identical), zebrafish zgc:173552 (99% identical), Caenorhabditis elegans his-17 (97% identical), Caenorhabditis elegans his-2 (97% identical), Caenorhabditis elegans his-32 (97% identical), Caenorhabditis elegans his-40 (97% identical), Caenorhabditis elegans his-42 (97% identical), Caenorhabditis elegans his-45 (97% identical), and 5 more. Paralogues in human: H3C1 (100% identical), H3C11 (100% identical), H3C12 (100% identical), H3C2 (100% identical), H3C3 (100% identical), H3C4 (100% identical), H3C6 (100% identical), H3C7 (100% identical), H3C8 (100% identical), H3C13 (99% identical), H3C14 (99% identical), H3C15 (99% identical), and 8 more.
Diseases named in the same sentence as H3C10 in open-access papers:
H3C10 is named in the same sentence as 3 diseases in open-access papers, as found by Europe PMC text mining. Sharing a sentence is not in itself a finding about the gene and the disease. The quoted sentences say what the papers report.
cancer (1 paper, 2024). A tumor composed of atypical neoplastic, often pleomorphic cells that invade other tissues. "Key transcripts such as H3C10, H1-2, PADI4, and others were identified as crucial in regulating the chromatin architecture and gene expression, which are essential for cancer progression and metastasis." (PMID 39000413, 2024). "Important transcripts such as H3C10, H1-2, PADI4, and others have been highlighted as critical in modulating the chromatin structure and gene expression, fundamental for the progression and spread of cancer." (PMID 39000413, 2024).
H3C10 also shares sentences with these, for which no sentence is quoted: gastric cancer (1 paper); systemic lupus erythematosus (1).